PAK6 (p21 (RAC1) activated kinase 6)
Diseases named in the same sentence as PAK6 in open-access papers (continued):
Sharing a sentence is not in itself a finding about the gene and the disease.
neuroblastoma (1 paper, 2024). Neuroblastoma (NB) is the most common solid, extracranial childhood tumor. "To investigate the involvement of PAK6 in ciliogenesis in brain cells, we generated polyclonal stable neuroblastoma SH-SY5Y cells overexpressing PAK6 via lentiviral vector (PAK6 OE) and, as control, downregulated PAK6-OE cells with LV-shRNA against PAK6 (PAK6 OE + PAK6 shRNA)." (PMID 39419978, 2024).
oesophageal cancer (1 paper, 2024). "The primary mechanism of action was found to be that LINC00680 acts as a competing endogenous RNA (ceRNA) that can sponge miR-423-5p, which in turn regulates the expression of p21-activated kinase 6 (PAK6) in oesophageal cancer cells." (PMID 38673838, 2024).
papillary carcinoma (1 paper, 2022). A malignant epithelial neoplasm characterized by a papillary growth pattern. "ERBB3/ERBB4/RAF1 kinases were activated in papillary carcinoma compared to other variants, PAK3/PAK6/CDK1 kinases were activated in NOS, and PRKACA/PRKACB/PRKACG kinases were activated in differentiation variants." (PMID 35659036, 2022).
small cell lung carcinoma (1 paper, 2025). Small cell lung cancer (SCLC) is a highly aggressive malignant neoplasm, accounting for 10-15% of lung cancer cases, characterized byrapid growth, and early metastasis. "Building upon the established role of P21 Activated Kinase 6 (PAK6) in tumor progression and chemoresistance pathways, we postulate its potential as a dual-function biomarker for small cell lung cancer (SCLC)." (PMID 40708824, 2025).
thyroid cancer (1 paper, 2017). "PAKs 1-4 and PAK6 are overexpressed in human thyroid cancer cell lines as well as in samples from patients with thyroid cancer." (PMID 28178642, 2017).
ulcerative colitis (1 paper, 2024). An inflammatory bowel disease involving the mucosal surface of the large intestine and rectum. "SLC6A14 negatively regulates PAK6 in a manner dependent on CCAAT enhancer binding protein beta (C/EBPβ), promoting epithelial cell ferroptosis in ulcerative colitis via the C/EBPβ–PAK6 axis." (PMID 39218897, 2024).
cancer (29 papers, 2011 to 2025). A tumor composed of atypical neoplastic, often pleomorphic cells that invade other tissues. "In colon and gastric cancer, the upregulation of PAK6 promotes cancer progression and chemotherapy resistance, while in clear cell renal cell carcinoma and hepatocellular carcinoma, its downregulation is linked to cancer progression and patients’ survival." (PMID 36429067, 2022). "Among the previously found cancer-hallmark survival-related genes (PAK6, SLC11A1, SULT1A1 and TUBB6), we observed that their differential expression still had a significant impact on survival for three of the genes (PAK6, SLC11A1 and TUBB6), when considering stage stratification." (PMID 34885088, 2021). "Activation of PAK6 is associated with various processes in cancer including metastasis." (PMID 27542207, 2016). "In the current study we ask whether downstream substrate specificity is conserved among the type II PAKs, whether a cancer-associated mutation that occurs in the type II PAK autoinhibitory region can activate PAK6, and whether co-crystallography might aid drug discovery for type II PAKs." (PMID 24204982, 2013). "p21-activated protein kinase 6 (PAK6) is a serine-threonine kinase belonging to the PAK family, which associated with many fundamental cellular processes in cancer including cell-cell adhesion, migration and apoptosis." (PMID 39696440, 2024). "While the role of PAK6 in cancer cells has been extensively investigated, the physiological function of the kinase in the context of brain cells is poorly understood." (PMID 39419978, 2024). "While being overexpressed in a number of cancers, under physiological conditions PAK6 shows a restricted tissue expression with enrichment in the brain." (PMID 39419978, 2024). "Functionally, PAK6 mediates cancer chemoresistance by enhancing homologous recombination (HR) to facilitate the DNA double-strand break repair." (PMID 35902562, 2022). "These genetic data are consistent with PAK4 being more functionally relevant than PAK5 and PAK6 for these cancers, even though the three enzymes have similar domain architectures and intrinsic substrate specificities." (PMID 35969127, 2022). "In the survival analysis of pan-cancer patients, high expression of PAK1, PAK2, PAK4, and PAK6 as well as the low expression of PAK7 was mainly associated with poor prognosis of tumor patients." (PMID 36064705, 2022). "PAK6 protein was localized in the cytoplasm of cancer cells, with strong staining in the cancer mucosa." (PMID 25426562, 2015). "The data presented here strongly suggest that PAK6 plays a role in cell–cell dissociation in different colony-forming cancer cell types." (PMID 24352566, 2014). "In contrast, PAK6 shows both oncogenic and oncosuppressive features, depending on the cancer type." (PMID 36429067, 2022). "Interestingly, PAK6 was upregulated in ARNTLKO, NR1D1KO cells and IPD female patients, suggesting a potential function for PAK6 linking cancer and neurodegeneration." (PMID 34885088, 2021). "PAK6 is a member of the p21-activated kinases (PAKs) that have fundamental roles in cellular processes such as adhesion, motility, and survival, as well as in cancer progression." (PMID 32547963, 2020). "In contrast, PAK3, PAK5, and PAK6 showed fewer alterations and did not exhibit strong associations with clinical outcomes in most cancer types, suggesting that their roles may be more tissue‐specific or context‐dependent." (PMID 39756822, 2025). "Therefore, PAK6 is also a potential therapeutic target for cancer treatment." (PMID 39233332, 2024). "Notably, PAK6 is overexpressed in certain cancer types, suggesting that PAK6 could serve as a potential therapeutic target for cancer treatment." (PMID 39233332, 2024).
cancer (continued). "Moreover, our study further identified that ATR inhibitor AZD6738 can be used as a combinational drug with oxaliplatin to overcome the chemoresistance to oxaliplatin induced by PAK6 in vitro and in vivo, providing a potential possibility for future consideration in clinical cancer treatment." (PMID 35902562, 2022). "Furthermore, the impact of somatic, acquired cancer mutations in PAK6 has not been studied, and structural biology techniques to identify potential ways to specifically target dysregulated type II PAKs have not yet been successful." (PMID 24204982, 2013). "Chronic exposure to cigarette smoke led to the activation of PAK6 in NSCLC, which regulates different processes in cancer cells." (PMID 31817720, 2019). "This suggests that PAK6-mediated regulation of MDM2 may exert both oncogenic and tumor-suppressive effects depending on the cancer context." (PMID 40650306, 2025). "Endocrine system development and cancer growth-related ceRNA regulation are found in TNBC; HOXA5, SCAPER, PAK6, PBX1, PITX1, and ALOX15B are the relevant genes involved; and hsa-miR-296-5p, hsa-miR-185-5p, hsa-miR-7851-3p, hsa-miR-3187-3p, and hsa-miR-10396b-5p are the relevant miRNAs involved." (PMID 37483500, 2023). "PAK6, which is overexpressed in cancer and phosphorylates β-catenin, might disrupt CRC cell–cell adhesion through the PAK6/IQGAP1/E-cadherin complex at the cell junction." (PMID 34439095, 2021). "The signaling landscape that accompanies Ephexin3 in various cancer types included the tyrosine kinase receptor MET and the tyrosine phosphatase receptor PTPRF, the serine/threonine kinases MARK2 and PAK6, the Rho GTPases RHOD, RHOF and RAC1, and the cytoskeletal regulator DIAHP1." (PMID 38003617, 2023). "PAK6, a serine-threonine kinase belonging to the class II p21-activated kinase (PAK) family, is generally overexpressed or hyperactivated in multiple human cancers, and acts as an oncogene by promoting a number of cancer hallmarks including cancer initiation, cell growth, EMT, and metastasis." (PMID 35255921, 2022). "Furthermore, a subsequent analysis on the possible role of the altered genes in CRC and IPD data sets in the survival of cancer patients (TCGA-COAD data sets) pointed to a significant influence on survival for eight of these genes (TUBB6, PAK6, SULT1A1, SLC11A1, TRAP1, FAM50B, SPON2, FES)." (PMID 34885088, 2021).
tumor (22 papers, 2015 to 2025). "ROC analysis revealed PAK6’s superior diagnostic performance compared to conventional serum tumor markers (STMs)." (PMID 40708824, 2025). "Elevated PAK6 was also found in HCC tissues compared with para-tumor tissues, and PAK6 expression was positively associated with the high proliferative ability of HCC and poor prognosis of patients." (PMID 36672500, 2023). "In the present study, stage II and III patients with high levels of tumor PAK6 expression showed an increased risk of tumor recurrence when treated with 5-FU-based chemotherapy after radical surgery." (PMID 25426562, 2015). "These signaling pathways are closely associated with the progression of SCLC, providing a strong theoretical basis for considering PAK6 as a tumor marker." (PMID 40708824, 2025). "In the study published in 2013, PAK1 expression was observed to be much higher in cell lines with high invasive/metastatic potential than in early-stage tumor cell lines, while PAK6 expression was detected at similar levels in all cell lines." (PMID 40864802, 2025). "Single-cell localization analysis of the risk genes demonstrated that only ADH7, SFN, WWC1, PAK6, and TEAD3 were detectable in the single-cell data, with TEAD3 being predominantly expressed in tumor cells." (PMID 41034991, 2025). "PAK6 also participates in tumor development through pathways such as ATR/CHK1, MAPK, and Wnt/β-catenins." (PMID 40708824, 2025). "We confirmed that endogenous PAK6 localizes at both the centrosome and the cilium, and positively regulates ciliogenesis not only in tumor cells but also in neurons and astrocytes." (PMID 39419978, 2024). "There were 129 GC patients from our hospital that were included in this study, and the patients were classified into PAK6-High group and PAK6-Low group according to the expression level of PAK6 of tumor tissues." (PMID 35902562, 2022). "On the other hand, in the treatment of combination of oxaliplatin and AZD6738, the tumor volumes of the PAK6 overexpression xenografts were significantly reduced as compared with the volumes of the monotherapy of oxaliplatin." (PMID 35902562, 2022). "In contrast to the oncogenic function of other PAKs, PAK6 has both oncogenic and tumor suppressive functions in different cancers." (PMID 33796531, 2021). "Accordingly, some genes (like HMGA2, MYO5B, and PAK6) had the opposite roles of AS events from the same parental gene in tumor and healthy tissues." (PMID 34628367, 2021). "Together, these data indicate that PAK6 overexpression in tumor cells is responsible for resistance to 5-FU-induced apoptosis." (PMID 25426562, 2015). "Our study indicated that tumor growth and tumor weights were significantly decreased in PAK6-KD tumor xenografts, especially when treated with 5-FU." (PMID 25426562, 2015). "As anticipated, the tumor growth and tumor weights were significant decreased in the PAK6-KD group compared to the control group." (PMID 25426562, 2015). "Additionally, the role of structural variants in PAK1 and the potential tumor‐suppressor functions of PAK5 and PAK6 represent important areas for future exploration." (PMID 39756822, 2025). "PAK6 is overexpressed in certain tumor types, including glioblastoma, triple-negative breast cancer, prostate cancer, and myelodysplastic syndromes, suggesting its potential for distinguishing tumor tissue from normal tissue with high specificity." (PMID 40708824, 2025). "Furthermore, the PAK6 localization in the mitochondrial inner membrane was confirmed by colloid gold labeling through immunoelectron microscopy, proving that PAK6 plays an important role in the mitochondria of tumor cells." (PMID 32194820, 2020). "In addition, the histopathologic analyses of these specimens revealed that a higher PAK6/ANT2 expression and a lower SIRT4 expression were significantly associated with the tumor size." (PMID 32194820, 2020).
tumor (continued). "Hence, PAK6 may play an important role in the movement of tumor cells, and may play an important role in stress response." (PMID 32194820, 2020). "We next studied whether PAK6 has any role in tumor cell motility." (PMID 27542207, 2016). "Our data provides a comprehensive comparison of DepMap dependency scores for PAK1, PAK2, PAK3, PAK4, PAK5, and PAK6, based on CRISPR analysis of 1100 tumor cell lines and RNAi analysis of 711 cell lines." (PMID 39756822, 2025). "PAK6, primarily located in the mitochondrial inner membrane, modulates SIRT4 stability through ubiquitin-mediated proteolysis, effectively decreasing its tumor-suppressive activity." (PMID 39796040, 2024). "As PAK6 enhances ANT2 phosphorylation to inhibit apoptosis, it simultaneously destabilizes SIRT4, further tipping the balance toward tumor survival." (PMID 39796040, 2024). "Our study in a PCa tumor xenograft model demonstrated impaired tumor angiogenesis with PAK1 or PAK6 gene knockdown, with PAK1 suppression exhibiting a superior anti-angiogenic effect than PAK6 suppression." (PMID 37190165, 2023). "In our study, PAK6 was found to be regulated by LINC00680 through RNA-seq analysis; PAK6 was highly expressed in ESCC tumor samples; a positive relationship was revealed between the expression of LINC00680 and PAK6 in ESCC tumor samples." (PMID 35255921, 2022). "We then searched for target genes that are clinically relevant (i.e. highly expressing in ESCC tumor tissues and positively correlated with poor prognosis of ESCC patients) as LINC00680, which led to the discovery of one gene named PAK6." (PMID 35255921, 2022). "One important member of the p21-stimulated serine/threonine protein kinase family is the p21-activated kinase 6 (PAK6) gene, which facilitates the repair of DNA double-strand breaks and mediates tumor chemoresistance through accelerated homologous recombination (HR)." (PMID 40136426, 2025). "This study, however, was an effect of PAK1 and PAK6 gene knockout in PCa cells on tumor angiogenesis, and not an effect of direct suppression of PAKs in endothelial cells." (PMID 37190165, 2023). "The tumor volumes of the PAK6 overexpression xenografts were indistinguishable from that of control cells in the untreated groups." (PMID 35902562, 2022). "In addition, due to the lack of PAK7 data in the GSVA database, we grouped 28 tumor patients according to the methylation status of PAK1, PAK2, PAK3, PAK4, and PAK6, respectively, and then analyzed the survival difference of tumor patients." (PMID 36064705, 2022).
infection (4 papers, 2015 to 2021). The state of being infected such as from the introduction of a foreign agent such as serum, vaccine, antigenic substance or organism. "Considering the functions of these genes, we believe that MAP3K21, PAK6, and MPZL1are strongly correlated with diarrhea induced by ETEC F4ac infection." (PMID 32547963, 2020). "Conversely, when we performed luciferase assays using a plasmid harboring a mutant version of the PAK6 mRNA 3′-UTR (the miR-23a binding sites were inactivated by site-directed mutagenesis), the luciferase activity of the mutant reporter was unaffected by the simultaneous infection with miR-23a." (PMID 25714010, 2015).
adenocarcinoma (2 papers, 2015 to 2016). A common cancer characterized by the presence of malignant glandular cells. "Moreover, differential methylation patterns between histologic subtypes were identified; hypermethylation in PAK6 and NOGOR is strongly correlated with adenocarcinoma." (PMID 26660311, 2015).
GI tumors (1 paper, 2024). "Group-II PAKs, including PAK6, have been particularly well studied in neoplastic processes (regarding stomach and other GI tumors), where they have been shown to be overexpressed in many tumors." (PMID 38254353, 2024).
heart disease (1 paper, 2022). "PAK family members participated in severe heart disease progression, and we observed that PAK6 possessed the potential binding site of miR-214-3p by using Target Scan Human 7.2 bioinformatics website." (PMID 35306484, 2022).
PAK6 also shares sentences with these, for which no sentence is quoted: colorectal cancer (2 papers); glioblastoma (2); renal cell carcinoma (2); schizophrenia (2); asthma (1); bladder cancer (1); chronic lymphocytic leukemia (1); diabetes (1); endometrial cancer (1); liver cancer (1); lung disease (1); neurodevelopmental disorder (1); non-small cell lung carcinoma (1); ovarian carcinoma (1); Parkinson's (1); polyp (1); prostate tumors (1).